EGFR (epidermal growth factor receptor)
Diseases named in the same sentence as EGFR in open-access papers (continued):
Sharing a sentence is not in itself a finding about the gene and the disease.
Sepsis (33 papers, 2009 to 2025). Sepsis is defined as life-threatening organ dysfunction caused by a dysregulated host response to infection. "Four patients had an EGFR mutation, of which two patients received targeted treatment with gefitinib; one patient died due to sepsis and another patient defaulted before any targeted therapy could be given." (PMID 36200011, 2022). "EGFRs have been recognised as key targets in anticancer therapy and EGFR inhibitors are increasingly used in the treatment of cancer with no reported renal toxicity, despite such patients being at increased risk of acute renal injury, predominantly due to sepsis." (PMID 23533381, 2013). "Together, our data suggest that EGFR-signaling represents a novel candidate of T cell dysregulation in sepsis and warrants further investigation." (PMID 41063987, 2025). "ELISA test results indicated that among pediatric patients, the five candidate biomarkers (AT III, CFD, Col1α1, EGFR, Thbs1) all showed varying degrees of decrease in diagnosing sepsis." (PMID 40702576, 2025). "Indirubin, the primary bioactive metabolite of Isatidis Folium, exerts protective effects against sepsis by targeting the EGFR/SRC/PI3K and NF-κB/MAPK signaling pathways in macrophages." (PMID 40144662, 2025). "Together, these results suggest a potential role for EGFR/SRC/PI3K signaling pathway in attenuating the effects of Indirubin on sepsis." (PMID 40144662, 2025). "Sepecifically, we validated that Indirubin, the major bioactive metabolite of Isatidis Folium, exerts its therapeutic effects in sepsis by modulating the EGFR/SRC/PI3K and NF-κB/MAPK signaling pathways." (PMID 40144662, 2025). "EGCG reduces EGFR and suppresses HIF-1α, HK2, PKM2, and iNOS expression, thereby attenuating sepsis-associated acute lung injury." (PMID 41322289, 2025). "To gain deeper insights into the role of EGFR in platelets during sepsis, we treated platelet with EGFR inhibitors treatment." (PMID 38632608, 2024). "Our findings highlight the central role of EGFR in platelet-macrophage interactions, which is crucial for reprogramming macrophage immune function and fostering antimicrobial activity during sepsis." (PMID 38632608, 2024). "Nevertheless, the regulatory role of EGFR on platelets in the context of sepsis remains largely unexplored." (PMID 38632608, 2024). "Conversely, low-risk patients exhibit excessive activation of WNT, Trail, JAK-STAT, EGFR, and VEGF compared to high-risk patients with sepsis." (PMID 38404591, 2024). "This study offers novel insights into platelet biology, emphasizing the significance of EGFR in facilitating platelet activation and modulating macrophage immune function during sepsis." (PMID 38632608, 2024). "In sepsis, EGFR can induce the apoptosis of CD4 + T lymphocytes by promoting the Warburg effect through TBK1/Glut1 signaling pathway." (PMID 38632608, 2024). "Using flow cytometry, we confirmed the expression of EGFR in platelets, and notable increase in EGFR expression was observed in platelets from the CLP sepsis model." (PMID 38632608, 2024). "Previous studies have demonstrated that phosphorylation of EGFR is necessary for TLR4-mediated activation of macrophages during sepsis." (PMID 38632608, 2024). "Collectively, our data elucidated a more in-depth mechanism of macrophages activation, and provided stronger evidence supporting EGFR as a potential therapeutic target for the treatment of sepsis." (PMID 36344490, 2022). "Altogether, our data elucidated a more in-depth mechanism of macrophages activation, and provided stronger evidence supporting EGFR as a potential therapeutic target for the treatment of sepsis." (PMID 36344490, 2022).
Sepsis (continued). "All these results indicated that LPS induces the activation of EGFR and promotes the expression of EGFR on the cell surface of macrophage in endotoxemia and sepsis." (PMID 36344490, 2022). "To evaluate the effect of membrane EGFR activation in M1/M2 phenotypic balance of macrophages in sepsis, we used LPS to stimulate BMDMs and RAW264.7 cells toward M1 phenotype." (PMID 36344490, 2022). "It has been reported that the inhibition of EGFR can improve the organ dysfunction induced by sepsis." (PMID 36341346, 2022). "Subsequently, inhibition of EGFR phosphorylation switches M1 phenotype to M2 phenotype and alleviates sepsis-induced acute lung injury." (PMID 36344490, 2022). "All these results indicate that inhibition of EGFR phosphorylation promotes M2 macrophage polarization during sepsis." (PMID 36344490, 2022). "A PPI network of the 49 common targets between acacetin and sepsis was constructed based on degree value screening, and EGFR, PTGS2, SRC and ESR1 were identified as the core targets." (PMID 34483900, 2021). "Collectively, current observations indicate that inhibition of EGFR protects kidney injury and is associated, at least in part, with significant inhibition of ERK1/2 and STAT3 signaling in mice with sepsis." (PMID 29207668, 2017). "Furthermore, Indirubin decreased the phosphorylation of EGFR and SRC in LPS-activated RAW264.7 cells, suggesting that its anti-inflammatory effects in sepsis are mediated through the EGFR/SRC/PI3K pathway." (PMID 40144662, 2025). "Moreover, we demonstrate that a higher frequency of circulating CD4+ and CD8+ lymphocytes express either the ligand (AREG) or receptor (EGFR) ex vivo, in sepsis, and expression of CD4+ lymphocyte EGFR was associated with several features of immunosuppression." (PMID 41063987, 2025). "In addition, the EGFR inhibitor erlotinib inhibited excessive activation of macrophages and reduced the secretion of pro-inflammatory cytokines and protected sepsis lung injury." (PMID 41293091, 2025). "The aim of this research was to investigate the effects of epidermal growth factor receptor (EGFR) monoclonal antibody-modified chemokine (C-X-C motif) ligand 8 (CXCL8) overexpression of macrophage (CXCL8@M)-derived exosomes miR-126a-3p (EGFR@CXCL8@exo-miR-126a-3p) on sepsis ALI." (PMID 41293091, 2025). "TGFA may activate downstream pathways such as Ras-MAPK and PI3K-AKT through the EGFR signaling pathway, a potential metabolic role in sepsis consistent with its significant enrichment in MAPK signaling pathways identified by GSEA analysis (P < .05)." (PMID 41305715, 2025). "Based on these findings, we hypothesized that Indirubin, the primary bioactive metabolite of Isatidis Folium, exerts its anti-inflammatory effects in sepsis by modulating the EGFR/SRC/PI3K signaling pathway." (PMID 40144662, 2025). "Our data demonstrated that EGFR is expressed at low levels in plasma during the early stages of sepsis; however, its likely involvement in these illnesses is unknown, and it may be implicated in the endothelial response to infection/inflammation." (PMID 40702576, 2025). "Additionally, it underscores the potential role of sustained AREG/EGFR signaling in promoting tissue restoration and survival in sepsis." (PMID 40292295, 2025). "Epidermal growth factor receptor (EGFR) is critical for platelet activation in sepsis." (PMID 38632608, 2024). "We propose that EGFR might play a crucial role in platelets to modulate the macrophage program towards a pro-inflammatory M1 phenotype during sepsis." (PMID 38632608, 2024). "EGFR phosphorylation is required for TLR4-mediated macrophage activation during sepsis." (PMID 36344490, 2022). "Interestingly, we found that the expression of cell surface EGFR was also increased in LPS-induced inflammation in macrophages, including mouse macrophage cell lines, mouse primary macrophages, and clinical sepsis patient primary monocytes." (PMID 36344490, 2022).
Sepsis (continued). "Moreover, we found that cell surface EGFR level regulates the M1/M2 polarizing phenotypic transformation of macrophages and influences sepsis-induced multiple organ injury through metabolic reprogramming." (PMID 36344490, 2022). "The pharmacological inhibition of the EGFR activation may represent a novel treatment for patients suffering from sepsis induced AKI by microbial infection." (PMID 29207668, 2017). "In addition, the inhibition of EGFR phosphorylation induces the transformation of macrophage M1 phenotype to M2 phenotype to exert anti-inflammatory effects, thereby attenuating the symptoms of acute lung injury triggered by sepsis." (PMID 39795251, 2025). "Therefore, we speculated that EGFR on platelets may regulate the manner of macrophage death, enabling a bidirectional regulation that could help elucidate the complex mechanisms of sepsis, which are still poorly understood." (PMID 38632608, 2024). "Then, network pharmacology screening revealed EGFR, PTGS2, SRC and ESR1 as the top four overlapping targets in a PPI network, and GO and KEGG analyses revealed the top 20 enriched biological processes and signalling pathways associated with the therapeutic effects of acacetin on sepsis." (PMID 34483900, 2021). "In sepsis- or LPS-induced ALI models, the epidermal growth factor receptor (EGFR) signaling pathway was activated in macrophages, which lead to macrophage activation and the secretion of pro-inflammatory cytokines [interleukin-1β (IL-1β) and IL-6]." (PMID 41293091, 2025). "Protein-protein interaction (PPI) network analysis revealed EGFR and SRC as the primary targets, suggesting their pivotal roles in sepsis therapy." (PMID 40144662, 2025). "EGFR in CD4+ T cells also regulates inflammation (e.g., limiting IL‐17‐mediated pathology) and promotes apoptosis in sepsis via Glut1 translocation." (PMID 40859900, 2025). "In pediatric patients diagnosed with sepsis on D1, plasma levels of AT III, Col1α1, and EGFR were diminished, subsequently increasing progressively, while CFD and Thbs1 remained down on D3 and recovered by D7." (PMID 40702576, 2025). "Following CLP-induced sepsis, the plasma abundance of AT III, CFD, EGFR, and Thbs1 was significantly reduced at D1, followed by a gradual increase and recovery, whereas Col1α1 did not exhibit this significant trend." (PMID 40702576, 2025). "Overall, LPS-induced extracellular AREG aggravated or triggered macrophage pyroptosis through the EGFR/TLR4/Myd88/NF-κB signaling pathway, providing promising treatment strategies for sepsis." (PMID 40292295, 2025). "The five putative sepsis plasma biomarkers (AT III, CFD, Col1α1, EGFR, Thbs1) revealed certain relationships with clinical laboratory indices related to hematology, biochemistry, blood gas analysis, coagulation function, and immune function." (PMID 40702576, 2025). "Firstly, 44 core targets of sufentanil in the treatment of acute lung injury in sepsis were discovered through network pharmacology, and key targets such as JAK2, SRC and EGFR were screened through PPI network construction." (PMID 39885929, 2024). "All potential targets of acacetin and sepsis were methodically obtained, and the top four overlapping targets in the PPI network were EGFR, PTGS2, SRC and ESR1." (PMID 34483900, 2021). "GO and KEGG analyses were performed, and the core targets of EGFR, PTGS2, SRC and ESR1 were input into the Omicshare database to identify the possible mechanism by which acacetin affects sepsis." (PMID 34483900, 2021). "Although EGFR was activated in endotoxin-induced AKI, little is known about the role and regulation mechanism of EGFR in sepsis AKI." (PMID 29207668, 2017). "It has been demonstrated that EGFR regulates the inflammatory function of macrophages, and EGFR can also induce the apoptosis of CD4(+) T lymphocytes through the TBK1/Glut1-induced Warburg effect in sepsis." (PMID 38632608, 2024).
Sepsis (continued). "The genes co-regulated by Acu-exo and sepsis were derived from multiple organs and systems, their interacting genes(HSP90AA1, GRB2, EGFR etc.)and signaling pathways(MAPK, TNF, JAK-STAT etc.)were involved in inflammation, immune regulation, metabolism, and cell proliferation and apoptosis." (PMID 37635258, 2023). "Notably, EGFR and SRC showed the highest affinity for Indirubin, with binding energies of −9.1 and −8.9 kcal/mol, respectively, suggesting their potential as critical therapeutic targets for sepsis." (PMID 40144662, 2025).
small cell carcinoma (33 papers, 2006 to 2026). A neuroendocrine carcinoma composed of small malignant cells which are often said to resemble "oat cells" under the microscope. "Other mechanisms include small cell carcinoma transformation, gene amplification of EGFR, ERBB2, and MET and additional mutations in PI3K, BRAF, and KRAS32–36." (PMID 33863951, 2021). "We identified 265 treatment-naïve patients with non-small-cell carcinoma, who had EGFR mutations (n = 159), KRAS mutations (n = 55), or ALK rearrangements (n = 51)." (PMID 27518729, 2016). "Eight harbored a concomitant EGFR p.T790M mutation and the other case showed small cell carcinoma transformation." (PMID 27304188, 2016). "We examined 32 SCLC and three lines from small cell cancers from extrapulmonary sites (extrapulmonary small cell cancers, ExPuSC), for somatic mutations and CNGs of EGFR pathway genes." (PMID 19238210, 2009). "EGFR mutations occur in 2 out of 11 small cell carcinoma patients." (PMID 36233370, 2022). "Initial histologic diagnoses included adenocarcinoma (n = 10), adenosquamous (n = 1), and combined small cell carcinoma with an adenocarcinoma component (n = 1), with eight having EGFR exon 19 deletions and four with EGFR L858R." (PMID 41256964, 2025). "Histologic transformation to high-grade neuroendocrine carcinoma—including small cell carcinoma—develops as a resistance mechanism to EGFR tyrosine kinase inhibitors (TKIs) in approximately 3% to 4% of patients with EGFR-mutant NSCLC." (PMID 41256964, 2025). "Mechanisms of resistance to osimertinib primarily include secondary EGFR mutations (e.g., C797S), MET and erythroblastic oncogene B-2 (ERBB2) amplification, or histological transformation to small cell carcinoma, among others." (PMID 38213544, 2023). "The phenotypic transformation to small cell carcinoma (SCCT) has been estimated to occur in approximately 3 to 10% of patients treated with an EGFR-TKI." (PMID 33816221, 2021). "Transformation to small-cell carcinoma is a known mechanism of resistance to EGFR-TKIs in adenocarcinoma." (PMID 34094904, 2021). "Fisher’s exact tests were done to assess the relationship between EGFR and subtype (excluding small cell carcinoma), PD-L1 and subtype (excluding small cell carcinoma), and RAS and subtype (excluding small cell carcinoma); none of the tests reached statistical significance (p>0.05)." (PMID 39570822, 2024). "Transformation to small cell carcinoma occurs frequently during treatment with first- or second-generation EGFR-TKIs; therefore, such transformation is a common phenomenon for all-generation EGFR-TKIs." (PMID 30625213, 2019). "Also, they presented more frequently with a large-cell or small-cell carcinoma and were less EGFR mutant." (PMID 27039176, 2016). "These include additional mutations in EGFR (40–60%) and mutations in PIK3CA (5%) and BRAF (1%), amplification of MET (5–10%) and ERBB2 (12%), phenotypic transformation such as to small cell carcinoma (3–14%) and the epithelial to mesenchymal transition." (PMID 27304188, 2016). "Studies have identified different mechanisms of acquired EGFR-TKI resistance, including a second-site EGFR T790M mutation, MET amplification, PIK3CA mutations, FGFR1 activation, epithelial-to-mesenchymal transitions and conversion to small cell carcinoma." (PMID 25823662, 2015). "The triplex can then bind both the CCAT1 promoter, determining its transcription, and the super-enhancer domains of epidermal growth factor receptor (EGFR), thus activating downstream MAPK signaling cascade with the effect of promoting small cell carcinoma tumorigenesis." (PMID 34830370, 2021).
cutaneous squamous cell carcinoma (32 papers, 2009 to 2026). "Considering human cutaneous squamous cell carcinoma, EGFR overexpression is observed in 70% of cSCCs and is associated with metastasis and poor outcome." (PMID 38785565, 2024). "Epidermal growth factor receptor signaling is associated with the pathogenesis of cutaneous squamous cell carcinoma." (PMID 31890219, 2019). "While specific investigations on cSCC remain limited, several studies employing cutaneous squamous cell carcinoma cell lines (e.g., A431) have confirmed the efficacy of EGFR/CD3 bispecific antibodies." (PMID 41333481, 2025). "Concomitant alterations in the MAP2K1 and FGFR3 genes, as it is in the present case, have been described in cases of cutaneous squamous cell carcinoma that presented a significant response to EGFR inhibitors (cetuximab)." (PMID 39273494, 2024). "In our study on cutaneous squamous cell carcinomas (cSCCs), we evaluated the expression levels of EGFR, Ki-67, and Cox-2, as well as the possible correlations between them." (PMID 38785565, 2024). "Studies in canine cutaneous squamous cell carcinomas have highlighted the role of EGFR in promoting the growth and survival of tumor cells." (PMID 38248333, 2024). "Specifically, the hedgehog signalling pathway has been targeted for basal cell carcinoma (BCC), while the epidermal growth factor receptor (EGFR) is a key target in cutaneous squamous cell carcinoma (cSCC)." (PMID 39458069, 2024). "LPCAT1 was found to contribute to cutaneous squamous cell carcinoma progression through EGFR-mediated protein kinase B and p38MAPK signaling pathways." (PMID 36307879, 2022). "A recent study has demonstrated that LINC00520 regulated the tumorigenesis and metastasis of cutaneous squamous cell carcinoma by targeting epidermal growth factor receptor (EGFR)." (PMID 35945579, 2022). "The first treatment options for cutaneous squamous cell carcinoma included conventional chemotherapy, epidermal growth factor receptor- (EGFR-) targeted therapy, and interferon." (PMID 35898688, 2022). "Prior studies of conventional chemotherapy or epidermal growth factor receptor inhibitors for advanced (ie, locally advanced cutaneous squamous cell carcinoma [laCSCC] or metastatic [mCSCC]) cutaneous squamous cell cancer enrolled ≤ 40 patients." (PMID 32578965, 2020). "Immunohistochemical analysis was used to detect the expression of AHR, CYP1A1, EGFR, and Ki-67 in 10 actinic keratosis (AK) cases, 10 Bowen disease (BD) cases, 20 cutaneous squamous cell carcinoma (cSCC) cases and 20 normal skin samples." (PMID 30144817, 2018). "In such cases, a combined approach using miR-634 ointment and EGFR inhibitors could potentially enhance both the effectiveness and the length of response in treating locally advanced cutaneous squamous cell carcinoma, compared to using EGFR inhibitors alone." (PMID 38785565, 2024). "EGFR expression may act as an indicator of disease recurrence or shorter patient survival in some cancers, especially in cutaneous squamous cell carcinoma (cSCC)." (PMID 34689164, 2021). "Likewise, in cutaneous squamous cell carcinoma, the inhibition of CD147, by using a chimeric anti-CD147 monoclonal antibody or a small interfering RNA against CD147, causes the reduction of EGFR." (PMID 34944575, 2021). "Furthermore, a combination of curcumin with anti-EGFR (epidermal growth factor receptor) monoclonal antibodies in cutaneous squamous cell carcinoma patients has been shown as a highly effective strategy in disease control in another clinical." (PMID 32927725, 2020). "Moreover, lycopene inhibited phosphorylation of EGFR in human cutaneous squamous cell carcinoma COLO16 cells." (PMID 31491956, 2019). "This experiment was performed to determine whether the inhibitory effect of GSPs on the cell invasion of head and neck cutaneous squamous cell carcinoma cells is mediated through its inhibitory effect on EGFR expression." (PMID 22188922, 2011).